ANGPTL8 (angiopoietin like 8)
Diseases named in the same sentence as ANGPTL8 in open-access papers (continued):
Sharing a sentence is not in itself a finding about the gene and the disease.
hypertriglyceridemia (continued). "The prediction power of ANGPTL8 for the occurrence of TG > 1.13 mmol/L (>100 mg/dL) was quite comparable to that for the occurrence of moderate hypertriglyceridemia > 1.69 mmol/L (>150 mg/dL) [OR (95% CI) per unit increase = 1.495 (1.225–1.826), p < 0.001, R2 Nagelkerke = 0.41]." (PMID 35736472, 2022). "In vitro studies demonstrated that ANGPTL8/betatrophin did not promote MIN6 cell proliferation, but increased triglyceride levels in the culture of HepG2 cells, which supports the possibility that inhibition of ANGPTL8/Betatrophin represents a therapeutic strategy for hypertriglyceridemia." (PMID 30929133, 2019). "Collectively, these results suggest that inhibition of ANGPTL8 could be a therapeutic strategy to ameliorate hypertriglyceridemia." (PMID 26739706, 2016). "ANGPTL8 had a significantly lower AUC in males, compared with females (AUC = 0.54 vs. AUC = 0.83; p < 0.0001) and showed no diagnostic ability in males to identify subjects with hypertriglyceridemia." (PMID 34959891, 2021). "ANGPTL8 inhibition may be a promising therapeutic avenue for the treatment of hypertriglyceridemia." (PMID 29719529, 2018). "The discovery of Angptl8 seems to complete the player set for LPL regulation, but it is puzzling that all the three Angptl members are LPL inhibitors, and that deficiency (overexpression) of any one of them results in hypotriglyceridaemia (hypertriglyceridaemia)." (PMID 27053679, 2016). "Apolipoprotein C-III (apoC3) and angiopoietin-like protein 8 (ANGPTL8), recognized as inhibitors of lipoprotein lipase, play a role in modulating hypertriglyceridemia." (PMID 39944202, 2025). "The direct implication of the ANGPTL3-4-8 model is that when ANGPTL8 is increased, LPL activity will be suppressed in the heart and skeletal muscle, resulting in accumulation of TG in the circulation (hypertriglyceridaemia)." (PMID 27053679, 2016). "Related studies have confirmed that expression of ANGPTL8 in ANGPTL3 knockout mice failed to promote hypertriglyceridemia." (PMID 37170504, 2023). "Both ANGPTL3 and ANGPTL8 interact as regulators of LPL activity, and both are targets for pharmacotherapeutic agents currently undergoing testing as potentially effective drugs in the treatment of hypertriglyceridemia." (PMID 34959891, 2021). "This further supports our findings, as high ANGPTL8 levels are thought to contribute to hypertriglyceridemia rather than high ANGPTL3 levels." (PMID 34293055, 2021). "Polyunsaturated fatty acids (PUFAs) have beneficial effects on hypertriglyceridemia although their effect on angiopoietin-like proteins (ANGPTLs), specifically ANGPTL3, ANGPTL4 and ANGPTL8 is unknown." (PMID 32153916, 2019). "Angiopoietin-like protein 8(ANGPTL8) and apolipoprotein CIII (apoCIII) were found to inhibit the activity of lipoprotein lipase (LPL) and disrupt the clearance of triglyceride-rich lipoproteins (TRLs), leading to hypertriglyceridemia." (PMID 30021607, 2018). "We conclude that ANGPTL8 is specific for the regulation of TG-rich lipoproteins through the LPL pathway and that therapeutically targeting ANGPTL8 for the treatment of hypertriglyceridemia or cardiovascular disease may have different outcomes than targeting ANGPTL3." (PMID 34461133, 2021). "With the intake of a high-fructose or high-sucrose diet, Fgf21 and Angptl3, rather than Angptl8, may be better targets for the improvement of hypertriglyceridemia." (PMID 30405056, 2018). "Furthermore, overexpression of ANGPTL8 in ANGPTL3-knockout mice failed to promote hypertriglyceridemia." (PMID 26739706, 2016). "Since ANGPTL3, ANGPTL4, and ANGPTL8 are all LPL inhibitors, the absence of anyone of them would break the balance of triglyceride metabolism in turn would lead to hypotriglyceridemia or hypertriglyceridemia." (PMID 37170504, 2023).
atherosclerosis (16 papers, 2018 to 2026). A disease characterized by the build-up of fatty material and calcium deposition in the arterial wall resulting in partial or complete occlusion of the arterial lumen. "DM type 2, atherosclerosis and non-alcoholic steatosis have all been linked to increased circulating levels of ANGPTL8." (PMID 36983346, 2023). "Third, the mechanisms underlying how ANGPTL8 affects atherosclerosis and AAA need further investigation." (PMID 37294581, 2023). "MSR1 expression can also be induced by angiopoietin-like protein 8 (ANGPTL8), a hormone linked to the regulation of lipid metabolism and the development of atherosclerosis." (PMID 36325338, 2022). "Elevated ANGPTL8 levels have been reported to be associated with atherosclerosis and hypertension." (PMID 34167540, 2021). "Moreover, elevated plasma levels of ANGPTL8 are associated with atherosclerosis." (PMID 34557469, 2021). "Increased ANGPTL8 levels are closely associated with higher AIP values, indicating a predictive value of ANGPTL8 in atherosclerosis in patients with T2D." (PMID 41953664, 2026). "Previous studies have found that circulating ANGPTL-8 levels are elevated in inflammation-related diseases, such as systemic inflammatory response syndrome (SIRS), T2DM, atherosclerosis, and NAFLD, are associated with disease severity." (PMID 41026696, 2025). "Findings have indicated an upregulation of ANGPTL8 expression in atherosclerotic mice, and the improvement of atherosclerosis was observed after knocking out ANGPTL8." (PMID 38107478, 2023). "The results of double immunofluorescence staining revealed that ANGPTL8 was highly expressed in macrophages during atherosclerosis." (PMID 37294581, 2023). "In the present study, our data suggest that ANGPTL8 knockout attenuated atherosclerosis, we further verified the direct role of ANGPTL8 in atherosclerotic plaque progression of ApoE−/−ANGPTL8−/− mice." (PMID 37294581, 2023). "So far, eight ANGPTLs have been discovered, from ANGPTL1 to ANGPTL8, which are involved in various biological and pathophysiological progress, including glucose and lipid metabolism, inflammation, angiogenesis and atherosclerosis." (PMID 37180779, 2023). "This connection has spurred researchers to investigate the role of ANGPTL8 in atherosclerosis progression." (PMID 38107478, 2023). "We found previously that treatment with adeno-associated virus vectors containing small hairpin (shRNA) against ANGPTL8 attenuated atherosclerosis formation in ApoE−/− mice." (PMID 37294581, 2023). "ANGPT3, ANGPTL4 and ANGPTL8 can induce endothelial dysfunction and promote dyslipidemia by suppressing the LPL activity, which is associated with a higher risk of atherosclerosis." (PMID 37180779, 2023). "Our previous study found that ANGPTL8 knockdown ameliorated atherosclerosis in ApoE−/− mice, whereas ANGPTL8 overexpression promoted plaque formation." (PMID 37294581, 2023). "So one possible explanation for the relationship between ANGPTL8 and c-IMT is that ANGPTL8 is involved in the pathogenesis of atherosclerosis through regulating TG levels." (PMID 30007407, 2018). "Multivariate binary logistic regression revealed that serum ANGPTL8 was significantly related to subclinical atherosclerosis [odds ratio (OR) 3.05 (95% CI 1.59–5.86), P = 0.001] without adjustment." (PMID 30007407, 2018). "Some researchers reported that high serum ANGPTL8 was significantly associated with a lower risk of cardiac events and cardiac death in patients with stable CAD, but other research showed that high ANGPTL8 levels promoted the development of atherosclerosis." (PMID 35851270, 2022). "However, circulating levels of ANGPTL8 have been reported to be elevated in diseases associated with inflammation, such as T2DM, atherosclerosis, and NASH." (PMID 34167540, 2021). "Consistently, inhibition of ANGPTL8 seems to prevent or improve atherosclerosis." (PMID 34582711, 2021).
atherosclerosis (continued). "Together our data may point towards a novel role for ANGPTL8 in the pathogenesis of atherosclerosis in type 2 diabetic patients, whereas in control subjects with normal glucose tolerance the potential deleterious effects of ANGPTL8 could still be compensated." (PMID 30007407, 2018). "Furthermore, we used ApoE−/−ANGPTL8−/− mice to evaluate the effect of ANGPTL8 on atherosclerosis." (PMID 37294581, 2023). "In conclusion, we found that ANGPTL8 knockout significantly inhibited the progression of AAA and atherosclerosis in ApoE−/− mice." (PMID 37294581, 2023). "ANGPTL8 knockout significantly inhibited the progression of AAA and atherosclerosis in ApoE−/− mice." (PMID 37294581, 2023). "To explore the role of ANGPTL8, we bred ApoE−/−ANGPTL8−/− mice to evaluate the effect of ANGPTL8 on AAA and atherosclerosis." (PMID 37294581, 2023). "The study was aimed to investigate the effects of ANGPTL8 on the function of high-density lipoprotein (HDL), which plays a protective role in atherosclerosis progression." (PMID 30409151, 2018). "We found that ANGPTL8 was mainly expressed in macrophages during AAA and atherosclerosis." (PMID 37294581, 2023). "Therefore, in the present study, we investigated the role of ANGPTL8 in AAA and atherosclerosis using ApoE−/−ANGPTL8−/− double-knockout mice." (PMID 37294581, 2023). "Plasma levels of ANGPTL8 are known to be higher in atherosclerotic patients, resulting in plasma LPL inhibition and the build-up of circulating lipoproteins, both of which contribute to inflammation and the pathogenesis of atherosclerosis." (PMID 36983346, 2023). "Previous studies have found that circulating ANGPTL8 levels are elevated in inflammation-related diseases, such as systemic inflammatory response syndrome (SIRS), T2DM, atherosclerosis, and NAFLD, and are associated with disease severity." (PMID 38107478, 2023). "When ANGPTL8 could not be efficiently cleaned, accumulated ANGPTL8 might cause dysregulated lipids metabolism in the kidney, leading to lipids accumulation in the artery wall, foam cells formation, atherosclerosis deterioration and glomerulosclerosis occurrence." (PMID 30021607, 2018). "First, serum levels of ANGPTL8 were increased in type 2 diabetic patients with subclinical atherosclerosis than in type 2 diabetic patients without subclinical atherosclerosis and control subjects." (PMID 30007407, 2018). "The analysis of the mediator role of TG in the relationship between ANGPTL8 and c-IMT in type 2 diabetic patients with subclinical atherosclerosis group showed similar results, such that TG may be considered as partial mediator." (PMID 30007407, 2018). "But the direct role of ANGPTL8 in the atherosclerosis has not been demonstrated." (PMID 37294581, 2023). "Moreover, a positive association was found between ANGPTL8 and c-IMT in both type 2 diabetic patients with and without subclinical atherosclerosis groups." (PMID 30007407, 2018). "In addition, we further found that serum levels of ANGPTL8 were significantly higher in type 2 diabetic patients with subclinical atherosclerosis group than that in type 2 diabetic patients without subclinical atherosclerosis group." (PMID 30007407, 2018). "ANGPTL8 presents a negative effect on HDL-mediated cholesterol efflux capacity and a strong link with subclinical atherosclerosis, and its levels are significantly increased in patients with coronary disease, proportional to disease severity." (PMID 32746907, 2020). "The mediation analysis revealed that TG partially mediated the positive relationship between ANGPTL8 and c-IMT in both type 2 diabetic patients with and without subclinical atherosclerosis groups." (PMID 30007407, 2018). "When we tested the mediator role of TG in the relationship between ANGPTL8 and c-IMT in type 2 diabetic patients without subclinical atherosclerosis group, in the first linear regression equation, ANGPTL8 was positively associated with TG (P < 0.001)." (PMID 30007407, 2018).
Hepatic steatosis (16 papers, 2017 to 2026). Steatosis is a term used to denote lipid accumulation within hepatocytes. "Angptl8 regulates lipid metabolism and participates in diseases, such as renal insufficiency and metabolic-associated fatty liver disease." (PMID 39458511, 2024). "Our results show that PWS patients harbor lower ANGPTL8 levels than obese controls and that ANGPTL8 levels are more closely associated with liver steatosis, than with body composition and metabolic homeostasis." (PMID 28600576, 2017). "In fact, circulating ANGPTL8 levels were negatively associated with indices of liver steatosis, i.e. transaminases and US-derived scores of steatosis, which are recognized non-invasive markers of liver impairment in obesity." (PMID 28600576, 2017). "Notably, epidemiological studies have demonstrated an association between ANGPTL8 and metabolic diseases, including hepatic steatosis; thus, posing it as a potential biomarker for diagnosis and monitoring." (PMID 40276549, 2025). "Interestingly, the circulating angiopoietin Like 8 (ANGPTL8) has already been associated with liver steatosis in PWS." (PMID 38034016, 2023). "ANGPTL8 levels correlate positively with insulin resistance and triglyceride levels which are both key contributors to hepatic steatosis and steatohepatitis progression." (PMID 40276549, 2025). "Hepatic steatosis, a hallmark of MASLD, increases the secretion of pro-oncogenic hepatokines such as fetuin-A and angiopoietin-like protein 8 (ANGPTL8), often in complex with ANGPTL3 or ANGPTL4." (PMID 41463398, 2025). "The strongest part of this study is that many previously unexplored topics including evaluation of noninvasive scores and the relationship between ANGPTL-8 and hepatic steatosis in patients with acromegaly are presented for the first time." (PMID 37590020, 2023). "In particular, serum ANGPTL8 inversely correlated with the severity of liver steatosis and was reported to be usually lower in individuals with PWS than in obese controls." (PMID 38034016, 2023). "Angptl8-ASO mice exhibited a significant reduction in liver steatosis and improved insulin sensitivity compared to control-ASO treated mice." (PMID 35295579, 2022). "Of note, the treatment with Angptl8 anti-sense oligonucleotides markedly alleviated HFD-induced hepatic steatosis in rodents, presumably due to ANGPTL8 promoting lipogenesis via upregulating nuclear sterol-regulatory element binding protein 1 (SREBP1)." (PMID 34944728, 2021). "Leptin deficient ob/ob mice treated with high fat diet show increased levels of circulating ANGPTL8 which is directly related to the grade of liver steatosis." (PMID 33451033, 2021). "ANGPTL8 levels are also positively correlated with hepatocellular lipid content and ANGPTL8 antisense oligonucleotide prevents hepatic steatosis." (PMID 29940978, 2018). "In conclusion, ANGPTL8 levels are lower in PWS than obese controls and are inversely associated with the severity of liver steatosis." (PMID 28600576, 2017). "After the removal of PWS status from the regression equation, ALT levels (standardized β = 0.39, p = 0.01) or the score of liver steatosis (standardized β = 0.35, p < 0.05), acted as independent predictors of ANGPTL8 levels." (PMID 28600576, 2017). "In the search for mechanisms to explain our observations, we noted that circulating ANGPTL8 paralleled the behaviour of crucial determinants of metabolic health, such as liver steatosis." (PMID 28600576, 2017). "Moreover, multiple regression analysis revealed that the liver steatosis contributed independently to 41.8% of variation in hepatic ANGPTL8 transcripts after controlling for age, sex and BMI." (PMID 34884755, 2021). "Importantly, hepatic ANGPTL8 mRNA was significantly downregulated after sleeve gastrectomy and RYGB, and a positive association of post-surgical ANGPTL8 transcript levels with liver steatosis and AST (r = 0.57, p = 0.002) was detected." (PMID 34884755, 2021).
Hepatic steatosis (continued). "In conclusion, ANGPTL8 levels are lower in PWS than obese controls and, overall, they seem to reflect the severity of liver steatosis." (PMID 28600576, 2017). "By a stepwise multivariable regression analysis, ANGPTL8 levels were independently predicted by PWS status (p = 0.01) and liver steatosis (p < 0.05)." (PMID 28600576, 2017). "With respect to obese controls, ANGPTL8 levels were significantly lower in PWS (p = 0.007) and overall correlated with transaminase levels and the severity of liver steatosis, as well as FFM (p < 0.05 for all)." (PMID 28600576, 2017). "Moreover, post-surgical hepatic ANGPTL8 transcripts were inversely related to liver TG content and transaminase AST, supporting the hepatoprotective action of ANGPTL8 against liver steatosis." (PMID 34884755, 2021). "Corroborating these findings, correlation analysis in the two groups as a whole showed significant positive correlations between ANGPTL8 and AST (r = 0.35, p < 0.05), ALT (r = 0.38, p = 0.01), as well as with the grading of liver steatosis (r = 0.36, p < 0.05)." (PMID 28600576, 2017). "In conditions of chronic overnutrition, both serum insulin and glucocorticoid levels increase, leading to a change in ANGPTL system homeostasis: chronic overexpression of ANGPTL8 in hepatocytes may determine augmented insulin resistance, lipogenesis, increased VLDL secretion, and liver steatosis." (PMID 33451033, 2021).